FCGR3A (Fc gamma receptor IIIa)
Diseases named in the same sentence as FCGR3A in open-access papers (continued):
Sharing a sentence is not in itself a finding about the gene and the disease.
infection (52 papers, 2010 to 2025). The state of being infected such as from the introduction of a foreign agent such as serum, vaccine, antigenic substance or organism. "Our results suggest that CNV of FCGR3A influences susceptibility to develop GBS following an infection with C. jejuni, albeit in a relatively small subgroup of patients with a recent C. jejuni infection (n = 126)." (PMID 40593358, 2025). "Future studies will be required to determine if CD57 expression is linked to increased risk or severity of infection, and how the development of FCGR3A-signaling defects is related to this biomarker." (PMID 37620306, 2023). "In a log-rank test, there was a trend in association between maternal FCGR3A genotype and time to infant infection (P = .053)." (PMID 26613093, 2015). "In a study of post-operative infection in liver transplant patients, individuals that were dually homozygous for the FcγRIIA-131H/H, polymorphism and the polymorphism in FCGR3A (F/F158 that reduces IgG binding affinity) were susceptible to blood-borne infections and increased mortality." (PMID 27909648, 2016). "We next examined time to infant infection using Kaplan–Meier analyses to determine whether maternal FCGR3A genotype was associated with a particular transmission mechanism." (PMID 26613093, 2015). "Next, we analyzed the DEGs in the dNK subsets (NCAM1+FCGR3A−dNK and NCAM1+FCGR3A+dNK) after infection." (PMID 38730500, 2024). "The significantly downregulated genes (NEAT1, TPM3, ZNHBA, CKLF, and OSBPL8) and the upregulated genes (ITMZC, IFNG, CD69, DNAJB9, and LYST) in NCAM1+FCGR3A+dNK cells after infection were also analyzed." (PMID 38730500, 2024). "The possible mechanistic roles of FCGR3A and haptoglobin in maternal circulation as pathophysiological links with inflammation/infection in the amniotic cavity warrant further investigation." (PMID 37024561, 2023). "SARS-CoV-2-specific transfer was linked to altered SARS-CoV-2-antibody glycosylation profiles and was partially rescued by infection-induced increases in IgG and increased FCGR3A placental expression." (PMID 33476549, 2021). "Infant FCGR3A heterozygotes were not at an increased infection risk compared with homozygotes in a Cox proportional hazards model (hazards ratio [HR], 1.18; P = .44)." (PMID 26613093, 2015). "We postulated that HIV transmission might be impacted by allelic variation in FCGR3A or FCGR2A, since these are important signaling receptors that will affect immune activation and susceptibility to infection." (PMID 21187939, 2010). "We measured abundance of low and high activity alleles in two Fc receptor genes, FCGR2A and FCGR3A, for persons with HIV disease, natural virus suppressors (HIV+, without disease) and healthy controls to show whether genotypes were associated with infection and disease." (PMID 21187939, 2010). "The observation that infant FCGR2A and FCGR3A genotypes do not influence infant infection or disease progression has important implications for treatment and therapy." (PMID 26613093, 2015). "In the absence of infection, genes such as FCGR3A and NK2, a transcription regulator, were also up-regulated in HP rats." (PMID 21698235, 2011). "In doing so, they were able to conclude that patients who maintained low levels of viremia (<1000 viral copies/ml) at 2.74 years after infection without ART exhibited a subset of proliferative cytotoxic NK cells (CD8- TRDC+ FCGR3A+) during the earliest stages of acute infection." (PMID 35185920, 2022). "Interestingly, two patients (P2 and P3), who maintained low levels of viremia (<1000 viral copies/ml) at 2.74 years after infection without ART, exhibited a subset of proliferative cytotoxic NK cells (CD8- TRDC+ FCGR3A+) during the earliest stages of acute infection." (PMID 35185920, 2022).
infectious disease (7 papers, 2014 to 2024). A disorder directly resulting from the presence and activity of a microbial, viral, or parasitic agent in humans. "The FCGR3A-p.Val176Phe replacement (rs396991, frequently referred as Val158Phe), which increases CD16A (FcγRIIIa) affinity for IgG, has been related to the clinical course of haematological, autoimmune and infectious diseases, and to monoclonal antibody therapy outcome." (PMID 34108956, 2021).
immune diseases (6 papers, 2014 to 2026). "The results showed that protein levels of INFG, IL2RG, and FCGR3A associated with immune diseases were evidently upregulated (p < 0.001), while CAM1 protein levels were significantly downregulated as the differentiation time prolonged (p < 0.01)." (PMID 40844079, 2025). "Through bioinformatics analysis, the core genes INFG, IL2RG, FCGR3A, and ICAM1 associated with immune diseases were screened and their expressions were also measured at the protein level." (PMID 40844079, 2025). "Collectively, IFNG, IL2RG, FCGR3A, and ICAM1 associated with immune diseases were selected from the core genes through manual screening." (PMID 40844079, 2025).
cardiovascular diseases (2 papers, 2022). "In cardiovascular diseases, FCGR3A is a major checkpoint for the control of immune surveillance, and modulation of NK cell functions can help limit vascular injury in some patients." (PMID 36420258, 2022).
psychiatric disorder (1 paper, 2021). A disorder characterized by behavioral and/or psychological abnormalities, often accompanied by physical symptoms. "Antidepressant medication can have anti-inflammatory effects, which aligns with our findings of reduced mRNA levels of the natural killer cell marker FCGR3A and the microglia markers IBA1 and P2RY12 in psychiatric disorder cases with a history of antidepressant use." (PMID 34911938, 2021).
renal disease (1 paper, 2006). "Of particular interest to the development of renal disease in patients with SLE is the reported association of renal disease with the low binding allele of FCGR3A (the FCGR3A*T allele), a finding supported by a recent meta-analysis." (PMID 17076550, 2006). "Since the frequency distribution of FCGR3A alleles does not vary significantly among the ethnic groups studied, the additional factors underlying the ethnic disparities in renal disease progression remain to be elucidated." (PMID 17076550, 2006).
FCGR3A also shares sentences with these, for which no sentence is quoted: lymphoma (13 papers); Hodgkins lymphoma (11); myeloma (11); non-Hodgkin lymphoma (7); immune thrombocytopenia (6); Allergy (4); anemia (4); Autoimmunity (4); chronic periodontitis (4); multiple myeloma (4); acute myeloid leukemia (3); B cell lymphomas (3); chronic lymphocytic leukemia (3); coronary artery disease (3); ischemic stroke (3); Kaposi's sarcoma (3); lung adenocarcinoma (3); Thrombocytopenia (3); bacteremia (2); bacterial infection (2); Burkitt lymphoma (2); cholangiocarcinoma (2); colitis (2); colon carcinoma (2); head and neck squamous cell carcinoma (2); hematologic malignancies (2); hepatocellular carcinoma (2); Immunodeficiency (2); lupus erythematosus (2); ovarian tumor (2).
A further 78 diseases each share a sentence with FCGR3A in 2 papers or fewer.